EGFR (epidermal growth factor receptor)
Diseases named in the same sentence as EGFR in open-access papers (continued):
Sharing a sentence is not in itself a finding about the gene and the disease.
tumor (continued). "Both tumour sample and HBCx-17 are negative for ERBB2 and oestrogen, and progesteron receptor, and the clinical sample presented a strong EGFR staining that the xenograft did not (data not shown)." (PMID 20877358, 2010). "The levels of membranous or cytoplasmic EGFR expression in RCC tissues were not correlated with sex, tumor grade, TNM stage or overall survival (P > 0.05)." (PMID 19747398, 2009). "Thirty tumours were negative for ER, HER2, CK5/6 and EGFR and were considered to be of the negative group." (PMID 19165203, 2009). "Of the 169 ER-negative tumours, 62 (14%) were also HER2 negative but CK5/6 and/or EGFR positive; these were considered to be of the basal-like group." (PMID 19165203, 2009). "Seventy-five tumours (16%) were HER2 positive, regardless of their ER, CK5/6 and EGFR status, and were considered to be of the HER2 group." (PMID 19165203, 2009). "In the HER2-negative cohort, one patient experienced a durable CR (23 weeks) and had a primary tumour with the following molecular characteristics: HER2 negative and EGFR negative; ER positive and PgR positive; low expression of PTEN and PIK3CA (E767K) SNP." (PMID 19844234, 2009). "Given that EGFR inhibitor-induced apoptosis in EGFR-mutant tumors is preceded by a pronounced cell cycle arrest, we hypothesized that imaging modalities reflecting tumor cell proliferation rather than glucose metabolism might afford even earlier measurements of tumor growth inhibition." (PMID 19079597, 2008). "The tumor cells were also negative for each of the basal markers, i.e., CK5/6, CK14, CK17, and epidermal growth factor receptor (EGFR)." (PMID 18559079, 2008). "We identified 13 out of 17 IBC tumours with EGFR and/or ErbB2 overexpression compared to only one non-IBC tumour with EGFR and/or ErbB2 overexpression (κ=0.742, P<0.0001)." (PMID 17700572, 2007). "Using tumour phenotype (IBC or non-IBC), ER expression and presence of transcriptionally active NF-κB as independent variables and EGFR and/or ErbB2 overexpression as dependent variable, a logistic regression was performed." (PMID 17700572, 2007). "The subdivision of tumors into 5 sub-branches shows a non-random distribution of tumor subtypes and immunohistochemical staining of KRT5/6, EGFR and KIT." (PMID 17910759, 2007). "C-fos levels increased twofold in Detroit 562 control tumours, whereas no significant change was documented in c-fos in HEP2, or in EGFR mRNA levels in either of the two models." (PMID 17342092, 2007). "It has previously been suggested that the basal-like tumor type cluster is most optimally identified by IHC when using a combination of positive CK5/6 and/or EGFR, and negative ER and HER-2 staining results as classification criteria." (PMID 17263897, 2007). "Two ER-negative and HER2-non-amplified tumor-derived cell lines, SUM149 and SUM102, have been previously shown to express EGFR and show basal-like expression profiles." (PMID 17663798, 2007). "The basal-like tumours were defined as having no expression of ER and HER2; 98 of them did express epidermal growth factor receptor and/or cytokeratin 5/6." (PMID 17088909, 2006). "Using in vitro analyses of the tumor-derived cell lines, we have found no significant physical or functional interaction between EGFR (erbB1) and erbB2 in the presence of EGF (data not shown)." (PMID 16168116, 2005). "Patients with EGFR+/HER3+ tumours had higher objective response rate (36.4 vs 9.9%, P=0.03) and time to progression (7.7 vs 2.7 months, P=0.03) than patients with EGFR− and/or HER3− tumours, but no significantly longer survival." (PMID 16288303, 2005). "A key finding is a lack of a close correlation between varying degrees of EGFR expression in tumour cells and their sensitivity to EGFR TKI inhibitors such that low-level EGFR tumours can be more sensitive than tumours with high receptor expression." (PMID 15150574, 2004). "Therefore, anti-EGFR-derived-peptide IgGs may not act directly on tumour cells." (PMID 15083186, 2004).
tumor (continued). "In RNA dot blot assays the expression of KRAS2, PDGFA, EGFR, or MYC was generally not increased in the tumour samples when compared to that in normal testicular tissue of the same patients although there was interindividual variation in mRNA levels." (PMID 1829952, 1991). "Although our in vivo model of EGFR-TKI resistance showed that the combination of osimertinib and volasertib demonstrated enhanced efficacy compared to monotherapy, it failed to achieve tumor regression." (PMID 41539998, 2026). "Young women have a higher incidence of tumors with poor prognostic features, including negative estrogen receptor (ER−) status, larger tumor size (> 2.0 cm), HER2 overexpression, epidermal growth factor receptor expression, lymph node involvement, and high nuclear grade." (PMID 41049962, 2025). "Unlike conventional approaches focusing solely on EGFR inhibition, dual targeting of LINC01559 and osimertinib achieved marked tumor regression, suggesting that disrupting this axis could prevent adaptive resistance." (PMID 40313617, 2025). "Tumor stage and TNM statuses did not significantly differ between the WT and mutant EGFR groups." (PMID 40429751, 2025). "Translation of these results to a pharmacological scenario has illustrated that combining daraxonrasib with afatinib, an irreversible EGFR/HER2 tyrosine kinase inhibitor, and SD36, a selective STAT3 PROTAC, also led to robust tumor regression without evidence of tumor resistance." (PMID 41159877, 2025). "By decreasing cholesterol and lipid raft levels in the plasma membrane, proprotein convertase subtilisin/kexin type 9 (PCSK9) boosts human epidermal growth factor receptor 1 and 3 (EGFR and HER3) activation, driving tumor growth and metastasis in triple‐negative breast cancer (TNBC)." (PMID 40192514, 2025). "The alcian blue staining on RKO tumor Formalin-Fixed Paraffin-Embedded (FFPE) section slides, with or without the pre-treatment of HYAL-Fc or EGFR × HYAL before the staining, demonstrated that both HYAL-Fc and EGFR × HYAL effectively degraded HA in the RKO tumor stromata." (PMID 41228205, 2025). "A proteogenomic study of 99 never-smoking Korean patients with EGFR- and ALK-wildtype LUAD identified four molecular subgroups with distinct clinical outcomes, based on previously defined tumour and microenvironment signatures applied to transcriptome and proteome data." (PMID 40849356, 2025). "Notably, a 38% reduction in tumor weight was observed following treatment with EGFR × HYAL, whereas no notable change was noted with EGFR × Null, highlighting the specific role of hyaluronidase in remodeling the tumor stroma." (PMID 41228205, 2025). "In our LUAD models, BACH1 expression remained unchanged at both the mRNA and protein levels upon RKIP overexpression, suggesting that this interaction may not be as relevant in EGFR‐mutant LUAD, reinforcing RKIP's tumor‐specific roles." (PMID 40720248, 2025). "Using mixed co‐cultures of EGFR− and EGFR+ tumor cells (not in ECM) with activated T‐cells, CD3xEGFR bsAbs have been shown to effectively trigger bystander killing when the proportion of EGFR− tumor cells was up to 70%." (PMID 40178291, 2025). "Interestingly, EGFR, also a well studied target in PDAC, is a top feature for both the tumor lines but not the CAF line." (PMID 39221276, 2024).
tumor (continued). "A more in-depth examination of differentially expressed transcripts between EGFR-expressing and -non-expressing MES-GSC driven tumours additionally exposed specific molecular distinctions between vascular patterns dominated by either angiogenesis or vesectasia." (PMID 38570528, 2024). "However, in a mouse model of LUAC driven by mutant EGFR, the absence of ERRFI1 accelerates both the onset and progression of the tumour." (PMID 39096122, 2024). "Our preclinical studies showed that EGFRBi-armed T cells (EGFR BATs) lyse both established and patient-derived GBM cell lines, and induce multiple rounds of proliferation, endogenous tumor-specific cytotoxicity, and Th1 cytokine release without affecting T cell viability." (PMID 38263486, 2024). "Interestingly, we observed strong positive correlations of B7-H4 with PI3K and pAKT (as well as EGFR, which can activate PI3K) signaling on tumor cells, but negative correlations between B7-H4 and PTEN expression, a negative regulator of PI3K activity." (PMID 38687247, 2024). "All these indicated that GPS inhibited the proliferation of tumor cells without inducing obvious toxicities, which may validate the results of in vitro data that GPS could modulate the EGFR/PI3K/AKT signaling pathway." (PMID 38212810, 2024). "This could be explained by the fact that although EGFR is overexpressed in 90% of HNSCC, it is not exclusively expressed on the surface of tumor cells, but is also present at lower levels on normal cells." (PMID 39406917, 2024). "Next, the results of univariate analysis showed that the factors associated with OS in CRC patients were age, gender, clinical stage, EGFR expression, VEGF expression, and infiltration level of CD8+ T cells and CD103+CD8+ TRMs (p < 0.05), whereas tumor location and MMR status were not (p > 0.05)." (PMID 38954030, 2024). "In recurrent tumors, genotype cluster 3 environments, with high frequencies of both EGFR-only amplified and EGFR/CDK4 co-amplified cells, lose their connection with hypoxic (phenotype cluster 4) and tumor-cell-rich nonvascularized immunodepleted environments (phenotype cluster 5)." (PMID 38805346, 2024). "The simultaneous targeting of EGFR and the nonreceptor tyrosine kinase PYK2/FAK synergistically inhibited the proliferation of TNBC cells in vitro and suppressed tumor growth in a mouse xenograft model, proposing a promising and efficient therapeutic strategy for basal-like TNBC." (PMID 38473804, 2024). "Similarly, the results showed that higher infiltration of CD103+CD8+ TRMs was associated with lower TNM stage and negative VEGF expression (p < 0.05) but was not correlated with age, gender, tumor location, MMR status, and EGFR expression (p > 0.05)." (PMID 38954030, 2024). "In the mouse model of tumors overexpressed with EGFR A431, compared to the control groups of each antibody, treatment with free α-EGFR and α-CD16/α-4-1BB NPs or α-EGFR NPs, and α-CD16/α-4-1BB NPs led to moderate delays in tumor growth (P=0.0046 and 0.0061 versus the nontreatment group)." (PMID 37457707, 2023). "CRC tumours, characterised by high filamin A (FLNA) expression, do not respond to anti-EGFR therapy in cetuximab treatment but may respond to c-MET receptor tyrosine kinase inhibitors." (PMID 38067326, 2023). "Adults with stage IV/recurrent NSCLC without EGFR/ALK aberrations were randomized 1:1:1 to nivolumab plus ipilimumab, nivolumab alone, or chemotherapy (patients with tumor PD-L1 ≥ 1%), or nivolumab plus ipilimumab, nivolumab plus chemotherapy, or chemotherapy (patients with tumor PD-L1 < 1%)." (PMID 37548831, 2023). "Myeloid-specific deletion of EGFR in mice resulted in fewer and smaller tumours in both APCmin/+ and AOM/DSS models, and EGFR expression in myeloid cells but not in intestinal epithelial cells was associated with tumour metastasis and shorter patient survival time." (PMID 38077324, 2023).
tumor (continued). "Similar PTEN upregulation and EGFR inhibition was also observed in tumor tissues from A549 tumor‐bearing nude mice treated with QTPlus‐AM21 and erlotinib in combination with QTPlus Ctrl not exhibiting any regulations on PTEN and EGFR expressions." (PMID 36412002, 2023). "Lastly, a study comparing the immunohistochemical expression of a panel of EGFR-related biomarkers in LUAD smokers vs. NS indicated that EGFR expression was higher in tumours from smokers, whereas pAKT was mainly overexpressed in tumours from never smokers." (PMID 37686122, 2023). "Importantly, killing of EGFR‐negative CHO cells was negligible, indicating tumor target‐specific redirection of NK cells by the herein generated NKp46 SEEDbodies eff−." (PMID 36775946, 2023). "It seems that EGFR expression decreases after NAC, and that it is not the level of expression that plays a prognostic role but rather the difference between initial expression and expression in the residual tumour." (PMID 38273853, 2023). "Fluorescence labeled antibodies against EGFR and VEGF showed high specificity for the target tumor; however, these antibodies could not overcome the disadvantages such as longer time to reaction after injection, and immunogenicity." (PMID 37228164, 2023). "Anti-EGFR agents were infrequently used in patients with mutant RAS (in <5% of patients as first line, and <2.5% of patients as second or third line), regardless of primary tumor location." (PMID 37760572, 2023). "In line with this study, we observed that HNSCC tumor cells expressing caveolin-1 could use EREG silencing, but not AREG silencing, to overcome oncogenic dependence on EGFR and develop resistance to CTX/irradiation combination therapy." (PMID 36899869, 2023). "Previous studies showed that activation of PD-1 signaling, indicative of immunosuppression, and the PI3K/AKT pathway correlates with EGFR TKI resistance, consistent with our observation of increased tumor-stroma interaction in the predicted-not-to benefit group." (PMID 36647832, 2023). "Additionally, since our study was focused on the effects of EGFR-TKI combined chemotherapy on immune function, tumor markers and oxidative stress, it did not address the effect of the treatment on the incidence of adverse reactions and overall survival rate." (PMID 37250563, 2023). "It was confusing that EGFR and ERBB2 had low expression in tumor tissue compared to normal tissue whether in GEO or TCGA data, perhaps due to the disadvantage of bulk sequencing." (PMID 38348352, 2023). "In our exploration of TK expression in feline malignancies, we found that while TKI expression has been investigated in 21 different tumor types, nearly half of these records are either single cases or merely report the lack of a single TK expression (KIT or EGFR)." (PMID 37835664, 2023). "We found that the average nucleus size of proliferating cells was dramatically increased in LAs (Normal, 7.64 ± 0.04 μm, EGFR, 11.4 ± 0.12 μm, KRAS, 11.1 ± 0.12 μm error SEM, p = 2.5 x 10−69), suggesting that these enlarged cells are not senescent but are contributing to tumor growth." (PMID 36201559, 2022). "EGFRvIII, a common mutant of EGFR which is continually activated even without ligand binding to the receptor, occurs after the pathogenesis of GBM to change the pattern of tumor growth and increase the intra-tumoral heterogeneity and resistance to targeted therapies." (PMID 35785151, 2022). "Alternatively, the phage itself, with or without partial activation of the EGFR, may interfere with aspects of the extracellular milieu such as ECM elaboration or structure, that can impact on tumor development." (PMID 36591314, 2022). "We hypothesized that chemokines that were elevated after coculture and not decreased after EGFR-TKI, despite EGFR-TKI-sensitive cell lines, could affect the oncogenic signaling of persistent tumor cells." (PMID 36612121, 2022).
tumor (continued). "Failure to downregulate EGFR by cetuximab and panitumumab in CRC may be common, as pre-treatment tumor EGFR expression level does not correlate with clinical response to the MABs." (PMID 35650607, 2022). "Taken together, these findings demonstrated that the ACh/ChAT increase was, at least in part, an adaptive response upon EGFR-TKI treatment, although we could not exclude the possibility of intrinsically high levels of the short ChAT isoform in tumor cells." (PMID 36048538, 2022). "To examine whether the CGA/EGFR/GATA2 circuit occurs in GC patients, we stained for GATA2 and p-EGFR in 31 paired tumor specimens from patients who did not respond to chemotherapy." (PMID 35289315, 2022). "Nevertheless, by BLT we could not identify an additional effect of IL-2 on EGFR CAR T cell and BDCA-2 CAR T cell expansion at the tumor, since an overall higher signal in the whole mouse ROI was detected in IL-2-treated mice." (PMID 35836798, 2022). "Once we had verified the ability of EVs to be efficiently distributed throughout the lung and to accumulate preferentially in hEGFR-positive tumor cells, we administered a single dose of NC ASO or miR-125b ASO-loaded EVs with or without EGFR targeting to tumor-bearing mice 5 days post-inoculation." (PMID 35547755, 2022). "However, circulating miR-155, miR-410, and miR-181a/b showed a negative correlation with tumor suppressive gene WNT5A (p < 0.0001, r = -0.671) and with oncogenes MET (p < 0.0001, r = -0.4778), EGFR (p < 0.0001, r = -0.5235, r = -0.5217)." (PMID 35646622, 2022). "Moreover, HER-2 and EGFR-targeted CAR-T cell therapies demonstrated toxicity not only for tumor cells but also for normal cells that shared the antigen (on-Target, off-Tumor Toxicity)." (PMID 35743107, 2022). "The samples were processed for Western blot of a lot of critical signal molecules known to be involved in tumor metastasis of CCA, including the oncogenic RTKs (EGFR, Her2, Her3, and c-Met); Src, one of the nonreceptor tyrosine kinase; JNK, one of the MAPK; and AKT, a downstream molecule of PI3K." (PMID 35625759, 2022). "A peptide (P75) that targets EGFR and HER2 was also chemically attached to the magnetosome surface, resulting in selective engagement of these magnetosomes to MDA-MB-468 and SKBR3 cells and higher accumulation in tumours in mice relative to non-target tissues." (PMID 35547173, 2022). "Moreover, the EGFR signal intensity levels of malignant tissue were lowered in the presence of EGFR CAR T cells but not BDCA-2 CAR T cells, indicating that the engineered therapeutic cells actively attacked the antigen-expressing tumor cells." (PMID 35836798, 2022). "Nevertheless, it was demonstrated that no expression of NKX2‐1/TTF‐1 exon 1 was frequently detected in EGFR and KRAS wild‐type tumours, suggesting that a tumour suppressive role of NKX2‐1_004 might be independent of such oncogenic alterations." (PMID 34014042, 2021). "Blocking either EGFR or VEGFR2 alone may still allow PI3 K/AKT and/or MAPK to remain activated, hence tumor growth may not be efficiently inhibited by single therapy." (PMID 33804477, 2021). "EGFR nuclear translocation is stimulated by radiation mediated by Cavelolin-1 (CAV-1), and CAV-1 knockdown radiosensitizes triple-negative breast cancer, a tumor type for which there are no current targeted therapies and poor prognoses." (PMID 34337349, 2021). "Tumor uptake of 111In-nimotuzumab followed a similar trend with high uptake (12.4 ± 1.3 %IA/g) in EGFR positive DLD-1 xenograft and less uptake (3.4 ± 1.1 %IA/g) in EGFR negative MDA-MB-435 xenograft." (PMID 33535661, 2021).